SOX9 (SRY-box transcription factor 9)
Diseases named in the same sentence as SOX9 in open-access papers (continued):
Sharing a sentence is not in itself a finding about the gene and the disease.
chondrosarcoma (continued). "Then we further confirmed SOX9 was the direct target of miR-494 in chondrosarcoma cells by using qRT-PCR and western blot." (PMID 26317788, 2015). "Then we employed qRT-PCR assay to measure the endogenous expression of SOX9 in the tissues of chondrosarcoma and chondroma." (PMID 26317788, 2015). "Works is also needed to clarify the mechanisms by which SOX9 activate Notch signaling pathway and upregulated E-cadherin expression in chondrosarcoma." (PMID 26317788, 2015). "More importantly, SOX9 expression was inversely correlated with miR-494 in the tissues of chondrosarcoma patients." (PMID 26317788, 2015). "A recent study showed knockdown of SOX9 resulted in apoptposis of human chondrosarcoma cell lines, which indicating SOX9 play an oncogenic role in chondrosarcoma." (PMID 26317788, 2015). "We demonstrated that miR-494 was functionally involved in suppressing cell proliferation, cell migration, and cell invasion of chondrosarcoma cells by directly binding to 3′-UTR of SOX9." (PMID 26317788, 2015). "Our results indicated that the expression of SOX9 at both mRNA and protein levels were significantly down-regulated in chondrosarcoma cells transfected with miR-494 mimics (P < 0.05)." (PMID 26317788, 2015). "Expression of SOX9 in human chondrosarcomas suggests that chondrosarcomas originate from a multipotent stem cell committed to differentiation along the chondrogenic pathway." (PMID 21647363, 2011). "We have identified genes in a human chondrosarcoma cell line whose expression is altered by the overexpression of the chondrogenic transcription factor SOX9." (PMID 17935617, 2007). "Interestingly, we found that SOX9 plays a significant role as a transcription factor in osteoclasts in chondrosarcoma." (PMID 39033089, 2024). "Moreover, Sox9 was reported to be a useful marker in distinguishing mesenchymal chondrosarcoma from other primitive small cell malignancies." (PMID 35760773, 2022). "Our observations present novel insight into the role of SOX9 in chondrosarcoma biology and could thereby help to overcome the obstacle of drug resistance and limited therapy options." (PMID 33076370, 2020). "Especially in terms of T-VEC treatment, it is necessary to understand the biological processes underlying the immune dysregulation in the chondrosarcoma cells lacking SOX9 to understand the limitation of this therapy option." (PMID 33076370, 2020). "Thus, we analyzed SOX9 protein expression and distribution in DDCS by means of a tissue micro array (TMA) of dedifferentiated chondrosarcoma tissue samples from different patients, with immunohistochemical (IHC) staining of SOX9." (PMID 33076370, 2020). "This points to a pro-survival role of SOX9 in chondrosarcoma cells during early cancer stages, promoting tumor development, growth and progression, but at the same time, SOX9 may act as an inhibitor for progression into dedifferentiated tissue." (PMID 33076370, 2020). "Additionally, G2 and 3 chondrosarcoma revealed an increased SOX9 expression compared to dedifferentiated chondrosarcoma." (PMID 33076370, 2020). "In summary, our data indicate that SOX9 is highly expressed in chondrosarcoma, while decreasing or losing SOX9 in a late-stage sarcoma may be a prerequisite for tumor progression into a dedifferentiated state." (PMID 33076370, 2020). "The analysis of chondrosarcoma cells after the knockdown and knockout of SOX9 was performed to determine the subsequent molecular impact on the carcinogenic properties, downstream targets of SOX9 and therapeutic resistance mechanisms." (PMID 33076370, 2020). "However, both SOX9 knockout clones enhanced the cytotoxic effect of doxorubicin in chondrosarcoma cells." (PMID 33076370, 2020). "This decrease in SOX9 in DDCS in comparison to high-grade chondrosarcoma indicates that SOX9 reduction may support the progression into dedifferentiated stages or could even be a requirement for it." (PMID 33076370, 2020).
chondrosarcoma (continued). "However, it must be kept in mind that these results were obtained with a grade II-derived chondrosarcoma cell line and that the role of SOX9 must be assessed as strictly stage specific." (PMID 33076370, 2020). "We claimed that a certain SOX9 threshold was required for avoiding genetic instability (polyploidy) and thus tumor development and progression, and that drug resistance and the sensitivity against the oncolytic virus was influenced by the SOX9 expression level in chondrosarcoma." (PMID 33076370, 2020). "Therefore, we observed a higher gene expression of SOX9, COL2A1, and COMP, the genes associated with chondrocyte maturation, in MSCs and chondrosarcoma cells treated with vitamin B6." (PMID 31683926, 2019). "Our results indicate that mutually exclusive expression of PEG10 and phosphorylated SMADs in combination with differentially expressed SOX9 is an index to distinguish between enchondroma and chondrosarcoma, while PEG10 and TGF-β signalling are mutually inhibitory in chondrosarcoma cells." (PMID 29044189, 2017). "This pattern was inversely correlated with miR-29 expression in their MSC differentiation system to form cartilage discs meaning that overexpression of Sox9 in chondrosarcoma cells leads to a decrease in expression of the miR-29 family, whilst knockdown of Sox9 increased the expression." (PMID 29038440, 2017). "In addition to PEG10, SOX9 was significantly attenuated in grade 1 chondrosarcoma compared with enchondroma." (PMID 29044189, 2017). "Our results showed downregulation of SOX9 efficiently inhibited the cell migration (P < 0.05), cell invasion (P < 0.05) and cell proliferation of chondrosarcoma cells (P < 0.05)." (PMID 26317788, 2015). "Moreover, our data demonstrated that SOX9, the essential regulator of the process of cartilage differentiation, was the direct target and functional mediator of miR-494 in chondrosarcoma cells." (PMID 26317788, 2015). "Moreover, our data demonstrated that SRY-related high mobility group-Box gene 9 (SOX9), the essential regulator of the process of cartilage differentiation, was the direct target gene and functional mediator of miR-494 in chondrosarcoma cells." (PMID 26317788, 2015). "Finally, we were able to prove positive regulation of AP-2ε gene expression in human chondrosarcoma cells by the transcription factor SOX9 via direct interaction with a consensus binding site within the proximal promoter region of AP-2ε." (PMID 26273614, 2015). "We found SOX9 was significantly upregulated in the tissues of chondrosarcoma (P < 0.05)." (PMID 26317788, 2015). "Consistent with the previous study, we found knockdown of SOX9 could inhibit the cell proliferation, cell migration, and cell invasion of chondrosarcoma cells." (PMID 26317788, 2015). "Finally, miR-494 was inversely correlated with SOX9 expression in the tissues of chondrosarcoma patients." (PMID 26317788, 2015). "Then, lv-SOX9 and miR-494 mimics were transfected into chondrosarcoma cells." (PMID 26317788, 2015). "Thirdly, using human chondrosarcoma cell line SW1353 transfected with miR-494 mimics, we validated that SOX9 was downregulated at mRNA and protein level, which was further confirmed by the luciferase reporter assay, suggesting that miR-494 directly binded to SOX9 3′-UTR in chondrosarcoma cells." (PMID 26317788, 2015). "SOX9 has been demonstrated to be highly expressed in chondrosarcoma." (PMID 26317788, 2015). "Furthermore, migration assays (P < 0.05), invasion assays (P < 0.05), wound healing assays (P < 0.05), and MTT assays (P < 0.05) showed that the exogenous expression of SOX9 rescued the phenotype induced by overexpression of miR-494 in chondrosarcoma cells." (PMID 26317788, 2015). "All these results suggest SOX9 may play an oncogenic role and is a crucial functional mediator of miR-494 in chondrosarcoma cells." (PMID 26317788, 2015).
chondrosarcoma (continued). "Previous study has demonstrated that SOX9 was upregulated in chondrosarcoma cells, and miR-145 could inhibit SOX9 expression by directly targeting its 3′-UTR." (PMID 26317788, 2015). "The sheared, cross-linked chromatin fragments of rat chondrosarcoma (RCS) cells were immunoprecipitated with either SOX9 antibodies or with non-specific IgGs." (PMID 20404928, 2010). "Our data indicate that SOX9 is essential for preventing genetic instability in chondrosarcoma cells and that a threshold of SOX9 expression/activity for this mechanism may exist, as we did not observe this dramatic increase in aneuploid and polyploid cells after SOX9 knockdown." (PMID 33076370, 2020). "Thus, we transiently reduced SOX9 expression in a chondrosarcoma cell line (HTB94, derived from a G2 chondrosarcoma) via siRNA, leading to a decrease in SOX9 gene expression and accordingly, to decreased protein expression by 80–90% compared to control cells (non-targeting siRNA = nt)." (PMID 33076370, 2020). "Thus, the combination of PEG10 and p-SMADs together with SOX9 might be used for differential diagnosis of chondrosarcoma and enchondroma." (PMID 29044189, 2017). "Fourthly, knockdown of SOX9 also significantly inhibited the cell proliferation, cell migration, and cell invasion of chondrosarcoma cell line in vitro, and exogenous expression of SOX9 could rescue the phenotype induced by overexpression of miR-494 in SW1353 cells." (PMID 26317788, 2015). "Downregulation of SOX9 could also inhibit proliferation and invasion of chondrosarcoma cells." (PMID 26317788, 2015). "And downregulation of SOX9 could also inhibit migration and invasion of chondrosarcoma cells." (PMID 26317788, 2015). "Thus, we performed luciferase reporter assay to verify whether miR-494 directly binded to the 3′-UTR of SOX9 in chondrosarcoma." (PMID 26317788, 2015). "It has been shown that the restoration of miR-145 expression by lentiviral transfection results in the downregulation of SOX9, ETV5, and MMP-2, leading to the reduced invasion and metastasis of Chondrosarcoma cells." (PMID 40429954, 2025). "SRY-box transcription factor 9 (SOX-9) is the master regulator of chondrogenesis and increases in chondrosarcoma tissue and is directly targeted by miR-145." (PMID 37568740, 2023). "In chondrosarcoma tissues, the expression of EXT1 and EXT2 usually has a significant reduction, whereas SOX9 has a higher expression." (PMID 35760773, 2022). "Other in vitro studies recently showed, that tumor progression involved SOX9 and CDKN1C repression in different chondrosarcoma cell lines." (PMID 33076370, 2020). "Therefore, the down-regulation of COL2A1 in our chondrosarcoma samples might be a result of gene mutation that is independent of a decrease in the upstream regulator, SOX9." (PMID 29044189, 2017). "Herein, we determined the effects of FYD on the expression of transcription factor SOX9 and its target gene collagen type II, alpha 1 (COL2A1) as well as the activation of Smad2/3 in interleukin- (IL-) 1β-stimulated SW1353 chondrosarcoma cells." (PMID 26770254, 2015). "Oncostatin (OSM), a member of IL-6 cytokine family, induces a hypertrophic differentiation, with reduced SOX9 and induced Cbfa1, Coll10, MMP13, VEGF, and RANKL expression in chondrosarcoma cells." (PMID 21647363, 2011). "SOX9, showing a homogeneous nuclear expression in mesenchymal chondrosarcoma, is negative in SCOS, which can be helpful for discrimination, as demonstrated in one of our cases." (PMID 38332052, 2024). "The 8N-peak especially increased remarkably in the cell clones lacking SOX9, indicating an important role of SOX9 for maintaining genetic stability and inhibiting numerical alterations of chromosomes in chondrosarcoma cells." (PMID 33076370, 2020). "Surprisingly, the role of SOX9 in chondrosarcoma is still not understood, although SOX9 is the master transcription factor of chondrogenesis." (PMID 33076370, 2020).
chondrosarcoma (continued). "Sox-9, a master regulator of chondrocyte differentiation, was shown to downregulate miR-29b both during chondrogenesis from a murine mesenchymal stem cell line and when it was transiently overexpressed in human SW1353 chondrosarcoma cell line." (PMID 28612031, 2017). "SOX9 might be used as a marker to distinguish grade 1 chondrosarcoma from enchondroma, while COL2A1 may be able to discriminate between grade 1 and 2 chondrosarcomas." (PMID 29044189, 2017). "Besides this, Liu and Lefebvre found that the regulatory trio of SOX9, SOX5 and SOX6 cooperatively work together to activate super-enhancers in a genome-wide way in rat chondrosarcoma cells." (PMID 26927636, 2016). "Moreover, miR-494 inhibited cell proliferation and invasion of chondrosarcoma cells in vivo and in vitro by directly binding to the 3′UTR of its functional mediator SOX9." (PMID 26317788, 2015). "As chromatin source for ChIP-on-chip experiments, we used rat chondrosarcoma cells (RCS cells), because these cells display many chondrogenic characteristics including secretion of specific cartilage ECM proteins and high contents of SOX9, SOX5 and SOX6." (PMID 20404928, 2010). "Thereby, we compared SOX9 gene expression in healthy cartilage (26 samples) with the expression in grade I (G1) chondrosarcoma (17 samples), grade II (G2) chondrosarcoma (39 samples), grade III (G3) chondrosarcoma (17 samples) and dedifferentiated chondrosarcoma (16 samples)." (PMID 33076370, 2020). "The SOX9 gene expression level was significantly increased in G1, 2 and 3 sarcoma compared to healthy cartilage, but is not changed significantly in dedifferentiated chondrosarcoma compared to the cartilage control." (PMID 33076370, 2020). "Indeed, this imbalance of SOX9 and SOX4 may contribute to the incomplete chondrogenic differentiation and persistent proliferation of chondrosarcomas." (PMID 29361725, 2018). "In addition, the chondrogenic master regulator, SOX9, showed differential expression between enchondroma and grade 1 chondrosarcoma, while expression of the cartilage-specific gene, COL2A1, was decreased in grade 2 chondrosarcoma compared with grade 1." (PMID 29044189, 2017). "We found that expression of the chondrogenic master regulator gene, SOX9, was strong in enchondromas and significantly diminished in grade 1 chondrosarcomas, while expression of the cartilage-specific collagen gene, COL2A1, was dramatically decreased in grade 2 chondrosarcomas." (PMID 29044189, 2017). "Hence, it is likely that Sox9 alone is not sufficient to trigger AP-2ε expression in this cell type in contrast to the SW1353 chondrosarcoma cell line, probably due to a missing coactivator in the mesenchymal cells." (PMID 26273614, 2015). "However, both SOX9 knockdown and knockout cells exhibit a strong increase in apoptosis, accompanied by a reduction of the anti-apoptosis mediator BCL-2 suggesting a potential direct connection between SOX9 and BCL-2 during chondrosarcoma progression to a dedifferentiated stage." (PMID 33076370, 2020). "Thus our data indicates miR-494 may play a tumor suppressive role but not a oncogenic role in chondrosarcoma and suppresses the proliferation and invastion of chondrosarcoma cells by decreasing the expression of oncogene SOX9." (PMID 26317788, 2015).
glioblastoma (33 papers, 2015 to 2026). The most malignant astrocytic tumor (WHO grade IV). "SOX9 was identified as a diagnostic and prognostic biomarker in glioblastoma, particularly in IDH-mutant cases." (PMID 40692865, 2025). "We demonstrated in vitro that USP18/SOX9 plays a significant role in glioblastoma malignancy and the maintenance of stemness and explored its underlying mechanisms." (PMID 40374599, 2025). "Through its USP domain, USP18 interacts with SOX9, stabilising the protein and thereby promoting the maintenance of glioblastoma stemness and the progression of malignant phenotypes." (PMID 40374599, 2025). "Our study underscores the potential of targeting the YY1/USP18/SOX9 axis as a therapeutic strategy for glioblastoma." (PMID 40374599, 2025). "Immunoprecipitation experiments revealed that USP18 knockdown significantly increased SOX9 ubiquitination in glioblastoma cells." (PMID 40374599, 2025). "Our results indicated that the knockdown of USP18 promoted the degradation of SOX9 in glioblastoma cells, thereby shortening its half-life." (PMID 40374599, 2025). "The upregulation of the NSC-like glioblastoma marker Sox9 in Sox10-KD tumors was confirmed at the protein level by immunohistochemical analysis." (PMID 39285246, 2024). "Immunofluorescence analysis of mouse glioblastoma also confirmed the enrichment of Sox9 and p27-positive cells in TMZ-treated animals (Fig. EV3H)." (PMID 39285246, 2024). "Next, we investigated the role of TMZ chemotherapy in the emergence of the p27/SOX9 double-positive state in human glioblastoma cells." (PMID 39285246, 2024). "qRT–PCR showed that siRNA transfection of Sox9 downregulated miR-204-3p expression in both glioblastoma cells and their exosomes." (PMID 36810326, 2023). "For example, miR-216b inhibited the proliferation and invasion of non-small cell lung cancer (NSCLC) cells by directly targeting SOX9, and miR-145 reduced the adhesion and invasion of glioblastoma cells by inhibiting the carcinogenic proteins of SOX9 and ADD3." (PMID 37328795, 2023). "To date, expression perturbation of LINC01132 has only been associated with oncogenic activities in ovarian cancer by regulating miR-431-5p/SOX9 axis and involved in hypoxia regulation in glioblastoma." (PMID 36071454, 2022). "We found that ARNT2 knockdown decreased the expression of SOX9, POU3F2 and OLIG2, transcription factors implicated in glioblastoma cell tumorigenicity, and repressed glioblastoma stem-like cell tumorigenic properties in vivo." (PMID 29149419, 2018). "In line with this evidence, association analysis in the human glioblastoma cohort from the TCGA showed an inverse correlation between MKP1 and SOX2 (r = −0.207, p value = 1.3e−06) and also with SOX9 (r = −0.169, p value = 1.7e−04)." (PMID 29284798, 2017). "Indeed, in the embryonic cortex in vivo and in neuroblastoma and glioblastoma cells in vitro, Ascl1SA6 is more efficient at turning on neuronal gene expression and less efficient at transactivating the Sox9 glial promoter compared to Ascl1." (PMID 36061596, 2022). "For instance, endothelial miR-30c repressed survival of tumors by inhibiting TGF-beta-induced Serpine1, while it attenuated growth of colorectal carcinoma tumors by directly targeting BCL9, and it reduced proliferation and migration of glioblastoma cells by directly targeting SOX9." (PMID 35212616, 2022).